GIP (gastric inhibitory polypeptide)
Diseases named in the same sentence as GIP in open-access papers (continued):
Sharing a sentence is not in itself a finding about the gene and the disease.
Obesity (continued). "The role of GIP signaling in glucose-mediated AgRP neuron inhibition is consistent with the anorexigenic effects and obesity treatment efficacy of GIPR agonists." (PMID 40857106, 2025). "The FDA has approved glucagon-like peptide-1 (GLP-1) receptor agonists such as Liraglutide, Semaglutide, and the GLP-1/gastric inhibitory polypeptide (GIP) dual agonist Tirzepatide for the treatment of obesity." (PMID 39980735, 2025). "This review article will focus on the specific functions of GLP-1, GIP, and PP metabolic hormones, and their implications in hyperinsulinemia, obesity, and dementia." (PMID 39857716, 2025). "The findings from trials investigating GLP-1RAs and dual GIP/GLP-1RAs in obesity and OSA represent a significant advancement in managing these conditions, yet there are critical aspects to analyze." (PMID 39857719, 2025). "Retatrutide is the first triple agonist (acting on GLP-1/GIP/glucagon receptors) with published phase 2 data in people with obesity as well as in people with T2D." (PMID 40741227, 2025). "A recent network meta-analysis including 27 RCTs and 15,584 participants evaluated efficacy and safety of seven GLP-1 RAs and polyagonists (GLP-1/GIP or GLP-1/GIP/Glucagon) for weight management in individuals with overweight or obesity." (PMID 41266905, 2025). "In examining the influence of overweight and obesity, we found significantly elevated levels of GIP and GLP-1 in women with PCOS and elevated weight, along with higher insulin and IR indices." (PMID 40806228, 2025). "Incretin-based therapies such as glucagon-like peptide-1 receptor agonists (GLP-1 RAs) or dual GLP-1/glucose-dependent insulinotropic polypeptide (GIP) RAs are highly effective treatments for T2D and obesity, producing substantial weight loss." (PMID 41011082, 2025). "The effects of GLP-1 and GIP on obesity, thermogenesis, and adipocyte activation are complex and modulated by several physiological and experimental variables." (PMID 41155633, 2025). "More recently, tirzepatide, a dual glucose dependent insulinotropic polypeptide (GIP) and GLP 1 receptor agonist, has shown even greater effectiveness, with 22.5% weight loss in adults with obesity." (PMID 40507203, 2025). "The incretin effects of GIP have sparked new development in current treatments for obesity, and by using GIP agonists, therapies have been developed to regulate glucose metabolism, increase β-cell function, and even manage/reduce systemic blood pressure." (PMID 39857716, 2025). "Obesity development can be attenuated by neutralizing antibodies to GIP or by GIP receptor antagonists." (PMID 40328980, 2025). "Background/Objectives: Glucagon-like peptide-1 (GLP-1) and glucose-dependent insulinotropic polypeptide (GIP) receptor agonists have revolutionised obesity and type 2 diabetes management through effective weight loss and metabolic regulation." (PMID 41464694, 2025). "This study shows that combining GLP-1 and dual GIP/GLP-1 agonists with a digital behavioral change model significantly improves MetS markers in individuals with obesity." (PMID 40146920, 2025). "GIP antagonism is also a potential obesity treatment as in preclinical studies improved the metabolic profile and reduced food intake." (PMID 38302593, 2025). "The approval of tirzepatide, a novel long-acting dual incretin agonist of both GLP-1 and another incretin, GIP, continues to create excitement for the development of anti-obesity medications." (PMID 40149944, 2025). "As a result, these latest generation of anti-obesity medications (AOMs) with GLP1RAs and GIP/GLP1RAs represent the fastest growth in prescribing of all pharmaceuticals and represent a landmark change in the approach to obesity treatment." (PMID 39389849, 2025). "In consequence, changes in the secretion and/or action of GIP have been shown to make important contributions to pathogenesis of obesity-diabetes plus a range of other disorders." (PMID 40024571, 2025).
Obesity (continued). "The FDA has approved GLP-1 receptor agonists such as Liraglutide, Semaglutide, and the GLP-1/GIP dual agonist Tirzepatide for the treatment of obesity." (PMID 39980735, 2025). "According to our findings and published data, oral semaglutide at a dose of 14 mg is significantly less effective for weight loss in individuals with obesity than tirzepatide (a dual GLP-1 and GIP agonist)." (PMID 40510489, 2025). "The advent of GLP‐1 receptor agonists (GLP‐1 RAs) and the dual GIP/GLP‐1 RA tirzepatide marks a paradigm shift in the treatment of obesity and the obese phenotype of HFpEF." (PMID 41309245, 2025). "Enhanced fertility and pregnancy have also been observed in women taking either long-acting GLP-1 or dual GLP-1/GIP mimetics for treatment of obesity." (PMID 40024571, 2025). "Amgen, on the other hand, supports a GIP antagonist strategy and is developing AMG-133, a molecule that combines GLP-1 agonism with GIP antagonism, for obesity treatment (NCT04478708)." (PMID 40590228, 2025). "Taken together, these findings suggest dual‐targeted GIP‐loaded photothermal NPs have the potential to treat obesity and related metabolic dysfunctions." (PMID 41256211, 2025). "GIP can paradoxically affect body weight because the inhibition of endogenous GIP action or exogenous administration of supraphysiological doses of GIP has anti-obesity effects." (PMID 39940910, 2025). "The development of the GLP1R/GIPR dual agonist tirzepatide brought new insights into the role of GIP in the treatment of T2D and obesity because it can reduce both plasma glucose and glycated haemoglobin more effectively than the GLP1R agonist semaglutide." (PMID 39576749, 2025). "Metabolic peptides such as GLP-1, GIP, and PP play crucial roles in regulating body weight, glucose homeostasis, obesity, and inflammation." (PMID 39857716, 2025). "Tirzepatide, a dual GIP/GLP-1 RA, sets a new standard in obesity management, being extremely effective for weight loss." (PMID 40283662, 2025). "The blunted weight-reducing effect of intracerebroventricular administered acyl-GIP in the brain-specific GIPR knockout mice indicates that the anti-obesity effect of GIP or the GIPR system is mediated via GIPR in the CNS." (PMID 39940910, 2025). "Whereas GLP-1 forms the basis for many glucose-lowering and anti-obesity drugs such as liraglutide and semaglutide, GIP-based therapeutics have lagged behind due to early concerns that GIP had only weak activity in the context of type 2 diabetes." (PMID 39441374, 2025). "Recently, tirzepatide has been approved by the FDA and EMA for obesity treatment as the first long-acting dual GIP and GLP-1 receptor agonist." (PMID 39929239, 2025). "As apparent from the parallel development of drugs combining GLP1R agonism with either GIPR agonists or antagonists for the treatment of obesity, GIP appears to have several, sometimes opposing, actions on the brain." (PMID 40166681, 2025). "The development and study of new molecules with dual, triple, or quadruple action targeting GLP-1, GIP, glucagon, and IGF-1 is important to cover as many pathogenic links of obesity with as few adverse effects as possible." (PMID 40649920, 2025). "The GIP-GIP receptor (GIPR) system is known to significantly contribute to the development of obesity." (PMID 39940910, 2025). "This hypersecretion results in an increase in nutrient uptake in cells specialized in fat storage (adipocytes), thus becoming a major factor in the development of obesity, as researchers have found that obese patients have a higher level of GIP." (PMID 39857716, 2025). "This aligns with published narrative syntheses describing Tirzepatide’s dual GIP/GLP-1 receptor mechanism as a key driver of its robust weight-loss effects across diverse clinical trials and obesity-management settings." (PMID 41516991, 2025).
Obesity (continued). "Subjects with obesity and insulin resistance had significantly higher fasting plasma glucose, insulinemia, glucagon, and GLP-1 levels and similar fasting GIP values compared with those with obesity and normal insulin sensitivity." (PMID 40649920, 2025). "More recently, the dual glucose-dependent insulinotropic polypeptide (GIP) and GLP-1 receptor agonist, tirzepatide, has shown even greater weight loss (~20%) and received approval for obesity treatment in 2023." (PMID 41154632, 2025). "Analogs of the incretin hormones glucagon-like peptide-1 (GLP-1) and glucose-dependent insulinotropic peptide (GIP) have become mainstays of obesity and diabetes management." (PMID 40857106, 2025). "This drove the conclusion that GIP is adipogenic and that the receptor should be antagonized to treat obesity." (PMID 40507574, 2025). "A phase 2 trial involving 338 adults with overweight status or obesity evaluated retatrutide—a triple agonist for GLP-1, GIP, and glucagon receptors—for weight loss over 48 weeks." (PMID 41153573, 2025). "Although GIP is primarily known to mediate the postprandial insulin response, it is considered as the obesity hormone given its role in the regulation of energy metabolism regulation." (PMID 39940910, 2025). "Retatrutide, a novel triple receptor agonist targeting glucagon-like peptide-1 (GLP-1), Glucose-Dependent Insulinotropic Polypeptide (GIP), and glucagon receptors, represents a groundbreaking advancement in obesity and T2DM pharmacotherapy." (PMID 40563436, 2025). "Immunoneutralization of GIP using specific monoclonal antibody attenuates the development of obesity in HFD-fed mice." (PMID 39940910, 2025). "Future research should investigate how GIP signaling influences orthodontic responses under systemic conditions such as diabetes or obesity, which are major indications for incretin therapy." (PMID 41516077, 2025). "Tirzepatide, a dual glucose-dependent insulinotropic polypeptide (GIP) and GLP-1 receptor agonist, promotes weight loss in patients with type 2 diabetes mellitus and obesity." (PMID 40492139, 2025). "Biologics like monoclonal antibodies/nanobodies expand GPCR targeting, with Glucagon-Like Peptide-1 (GLP-1) agonist/Gastric Inhibitory Polypeptide (GIP) antagonist combos showing efficacy against obesity/diabetes." (PMID 40552145, 2025). "GLP1/GIP/GCG is the only combination of hormone receptor agonism under investigation as a unimolecular triple agonist in phase 2 or 3 trials for obesity." (PMID 40741227, 2025). "Glucagon-like peptide-1 receptor agonists (GLP-1 RAs) and glucose-dependent insulinotropic polypeptide/GLP-1 receptor agonists (GIP/GLP-1 RAs) are emerging as effective treatments for obesity and cardiometabolic disease." (PMID 39852297, 2025). "The key pathophysiological changes observed in T2DM and obesity explain why GLP-1 became a successful drug target while GIP was initially overlooked." (PMID 41515907, 2025). "Dual GIP/GLP-1 receptor agonists offer promising therapeutic options for obesity and metabolic disorders." (PMID 40282969, 2025). "Tirzepatide, a once weekly dual agonist of GIP and GLP-1 receptors, is used for the treatment of both obesity and type 2 diabetes, leading to significant weight loss that is greater than seen with GLP-1 analogs alone." (PMID 40590228, 2025). "Acute central administration of acyl-GIP improved body weight and food intake in mice with diet-induced obesity and increased cFOS neuronal activity in the ARC, DMH, ventromedial hypothalamus, and LHA." (PMID 39940910, 2025). "Background and Objectives: GLP-1 receptor agonists (GLP-1 RAs; ATC A10BJ) and dual GLP-1/GIP agonist (ATC A10BX16) have expanded rapidly due to strong evidence in type 2 diabetes, obesity and metabolic dysfunction-associated steatotic liver disease (MASLD)." (PMID 41470212, 2025).
Obesity (continued). "MBS should be prioritized in patients with larger weight loss required and those with severe obesity-related comorbidities, such as T2D or intolerance to GLP-1 RA (GIP RA)." (PMID 40227854, 2025). "Both fasting and postprandial GLP-1 levels are lower in individuals with obesity compared to normal-weight, while GIP levels have been reported to be higher in people with obesity in both basal and stimulated states." (PMID 40687579, 2025). "The results showed that GIP/ICG@P/R8 NPs exerted superior effects in curbing obesity progression in diet‐induced obesity (DIO) mice." (PMID 41256211, 2025). "By contrast, down-regulation of GIP and resistin and leptin had been reported to be beneficial for obesity or diabetes treatment." (PMID 41356823, 2025). "GIP or GIPR inhibition protects mice from diet-induced obesity, and administration of long-lasting GIP derivatives or transgenic overexpression of GIP has an anti-obesity effect." (PMID 39940910, 2025). "Individuals with obesity exhibited lower ghrelin, GIP, and resistin, but higher C-peptide, insulin, and leptin compared to controls." (PMID 41155711, 2025). "The physiologic and pathophysiologic role of GIP as an adipogenic factor in humans provides an initial rationale for the development of GIPR antagonists to treat obesity." (PMID 40507574, 2025). "Glucagon-like peptide-1 (GLP-1) and glucose-dependent insulinotropic polypeptide (GIP) receptor agonists (RAs) mimic naturally occurring GLP-1 and GIP and are highly effective anti-diabetic and anti-obesity agents." (PMID 39964126, 2025). "GIP-induced vasodilation is blunted in adipose tissue of people living with obesity and insulin resistance, and in healthy humans upon antagonism of GIPR, and normalizes upon weight loss and restoration of insulin sensitivity." (PMID 40024571, 2025). "In individuals with obesity, GIP hypersecretion in response to glucose or a mixed meal is unrelated to hyperinsulinemia and is only observed after ingestion of a high calorie meal, potentially as consequence of an increased rate of gastric emptying." (PMID 40024571, 2025). "Incretins, such as glucagon‐like peptide‐1 (GLP1) and glucose‐dependent insulinotropic polypeptide (GIP), have advanced the treatment landscape of obesity to a new pinnacle." (PMID 39495024, 2025). "In view of this, a widespread search of SCOPUS, PubMed, and CENTRAL was performed using the following string” (obesity or insulin resistance) AND (tirzepatide or Dual GIP and GLP-1 Receptor Agonist)." (PMID 38978621, 2024). "The striking benefits of drugs that act as GLP-1 receptor agonists or agonists for both GLP-1 and GIP have provided novel and powerful tools to treat obesity and T2D." (PMID 38785817, 2024). "There are now several studies investigating the independent effects of GIP on obesity models in rodents and humans and how it appears to modulate glucose and lipid metabolism, as well as insulin signaling at the level of the AT." (PMID 38579777, 2024). "Of particular interest to obesity are glucagon and the incretin hormones, glucose-dependent insulinotropic polypeptide (GIP) and glucagon-like peptide-1 (GLP-1)." (PMID 38087928, 2024). "Tirzepatide, a dual GIP and GLP-1 receptor agonist, at a dose of 15 mg for 72 weeks, has also been associated with important weight loss (20.9%) in people with obesity." (PMID 39420906, 2024). "Tirzepatide, a promising agent that exhibits GLP-1/GIP co-agonism, significantly reduced body weight across all doses in adults with obesity." (PMID 39065679, 2024). "On the other hand, chronically elevating GIP levels in a transgenic mouse model exhibited reduced diet-induced obesity." (PMID 39114288, 2024). "Notwithstanding, significant general GIP overexpression prevents obesity and lowers inflammatory markers in mice." (PMID 39201336, 2024). "Delineating the spatial contribution of GIPR cells for the anti-obesity effects of acyl-GIP is key for a better understanding of this important new class of drugs." (PMID 38492844, 2024).
Obesity (continued). "Recently, a gut–brain axis has been discovered that links the GIP effect on hypothalamic metabolic signaling to obesity-related leptin resistance." (PMID 39201336, 2024). "Co-agonists at the receptors for glucagon-like peptide-1 (GLP-1) and the glucose-dependent insulinotropic polypeptide (GIP) are among the best-in-class drugs to treat obesity and type 2 diabetes." (PMID 38492844, 2024). "A GIP-GLP-1R coagonist is now used to treat people with T2D and produces substantial weight loss, resulting in its approval for treatment of obesity in 2023." (PMID 38226625, 2024). "Studies conducted so far have shown that the endogenous GIP-GIPR system has a significant impact on the development of obesity." (PMID 39408213, 2024). "Along this line, experimental mice overexpressing GIP were characterized by a reduction in diet-induced obesity and steatosis." (PMID 38612640, 2024). "In another 48-week phase 2 study including obese patients, weekly triple hormone (GLP-1/GIP/GCG) RA retatrutide (RETA: LY3437943) was investigated for obesity treatment in 338 obese patients, and 98 of those also suffered from MASLD." (PMID 38612640, 2024). "Studies conducted on animal models with diet-induced obesity have shown that these subjects display hyperplasia of K cells and increased GIP production." (PMID 39408213, 2024). "We aimed to investigate the fasting and stimulated levels of GDF15, total and H-specific, glucose-dependent insulinotropic polypeptide (GIP) and C-peptide, in two physiology interventional studies: one focusing on obesity, and the other on MASLD." (PMID 38762719, 2024). "Yet the postprandial secretion of GIP was markedly accentuated in the normal-weight group compared with people with obesity (p-treatment = 0.008), peaking at t = 120 min, in contrast with a delayed secretion and peak at t = 180 min in the obesity group." (PMID 38762719, 2024). "The effectiveness of the GLP-1/GIP co-agonist tirzepatide for obesity management is being investigated in the SURMOUNT study program." (PMID 38329549, 2024). "Our study uncovers novel data on the physiology of GDF15, GIP, and C-peptide in leanness, obesity, and MASLD." (PMID 38762719, 2024). "As noted, individuals with obesity exhibit elevated fasting levels of GIP, as well as excessive GIP secretion following meal consumption." (PMID 39408213, 2024). "The investigation of combinations involving GLP-1, gastric inhibitory polypeptide (GIP), islet amyloid polypeptide, glucagon, and leptin has revealed their potential to enhance weight loss in adults with obesity and type 2 diabetes." (PMID 39065679, 2024). "The apparent synergy between GLP-1R mimetics and GIPR antagonists has been exploited elsewhere in the pursuit of GIP MABs for obesity management." (PMID 38861364, 2024). "Analogues of GLP-1, alone or in combination with GIP, are used pharmacologically to treat type 2 diabetes and obesity." (PMID 38490484, 2024). "Impaired GIP signaling has been correlated with obesity and T2DM; however, the exact pathophysiological mechanisms have not been fully elucidated." (PMID 38612640, 2024). "In fact, it has been suggested that, in obesity, elevated circulating GIP levels lead to the activation of EPAC/Raf1 signaling and this is an important condition for inducing neural leptin resistance." (PMID 39201336, 2024). "It was therefore suggested that GIP contributes to the development of obesity by promoting lipid accumulation in VAT." (PMID 39408213, 2024). "The genetic or pharmacological blockade of GIPR attenuates obesity development in rodents, whereas GIP overexpression reduces diet-induced obesity and improves glucose metabolism." (PMID 36834794, 2023). "The circulating level of GIP is increased in obesity as it regulates lipid metabolism and adipocyte biology." (PMID 37208555, 2023).